HOXC13 (homeobox C13)
Description:
Transcription factor which plays a role in hair follicle differentiation. Regulates FOXQ1 expression and that of other hair-specific genes (By similarity).
Synonyms: HOX3G; ECTD9; HOX3
Tractability: PROTAC: ubiquitination databases record sites on it.
Gene: Protein-coding gene on chromosome 12 (53,938,831 to 53,946,544, forward strand). Ensembl gene ENSG00000123364.
Subcellular location: Nucleus
Gene Ontology:
Molecular function: DNA-binding transcription factor activity; DNA-binding transcription factor binding; protein binding; sequence-specific double-stranded DNA binding; transcription cis-regulatory region binding; DNA-binding transcription factor activity, RNA polymerase II-specific; RNA polymerase II cis-regulatory region sequence-specific DNA binding; chromatin binding; DNA binding; DNA-binding transcription activator activity, RNA polymerase II-specific
Biological process: positive regulation of DNA-templated transcription; anatomical structure morphogenesis; regulation of transcription by RNA polymerase II; positive regulation of transcription by RNA polymerase II; regulation of DNA-templated transcription
Cellular component: chromatin; nucleus
Genetic constraint (gnomAD): Loss-of-function variants: 10 observed, 20.49 expected, observed/expected ratio (o/e) 0.49, 90% interval 0.3 to 0.83. The synonymous counts are far from expectation, so gnomAD's model fits this gene poorly and the ratio says little. Missense variants: 439 observed, 400.12 expected, observed/expected ratio (o/e) 1.1, 90% interval 1.01 to 1.19. Synonymous variants: 233 observed, 184.4 expected, observed/expected ratio (o/e) 1.26, 90% interval 1.13 to 1.41.
Homologues: Orthologues: chimpanzee HOXC13 (100% identical), pig HOXC13 (99% identical), guinea pig HOXC13 (99% identical), macaque HOXC13 (99% identical), mouse Hoxc13 (98% identical), rat Hoxc13 (98% identical), dog HOXC13 (97% identical), zebrafish hoxc13a (72% identical), tropical clawed frog HOXC13 (69% identical), zebrafish hoxc13b (58% identical). Paralogues in human: HOXA13 (51% identical), HOXD13 (45% identical), HOXB13 (40% identical), HOXA11 (21% identical), HOXD11 (20% identical), HOXC11 (18% identical), HOXD9 (17% identical), HOXA10 (16% identical), HOXA5 (16% identical), HOXB9 (16% identical), HOXC12 (16% identical), HOXD10 (16% identical), and 30 more.
Diseases named in the same sentence as HOXC13 in open-access papers:
HOXC13 is named in the same sentence as 61 diseases in open-access papers, as found by Europe PMC text mining. Sharing a sentence is not in itself a finding about the gene and the disease. The quoted sentences say what the papers report.
breast carcinoma (7 papers, 2017 to 2025). "In this study, we explored the role of the cGAS-STING pathway in breast cancer immunotherapy resistance, particularly focusing on the pivotal role of the gene HOXC13." (PMID 40861477, 2025). "Our study highlights the critical role of the cGAS-STING pathway, molecular subtypes, and the miR-26a-5p/HOXC13 axis in breast cancer immune modulation and therapy response." (PMID 40861477, 2025). "In breast cancer, HOXC13 is specifically overexpressed and has a poor prognosis for patients and was strongly correlated with N stage and M stage." (PMID 38057852, 2023). "The miR-26a-5p/HOXC13 axis is pivotal in shaping breast cancer immunity and therapy response." (PMID 40861477, 2025). "Finally, the immunotherapeutic effect of HOXC13 in breast cancer was explored, and results showed that the group with higher expressed HOXC13 held higher anti-PD1/PDL1 response rates in four independent cohorts." (PMID 40861477, 2025). "Moreover, miR-26a-5p, a microRNA previously identified as a suppressor in breast cancer, was demonstrated to regulate HOXC13." (PMID 40861477, 2025). "The HOXC13 and CSNK2B expression increase in breast cancer and play a key role in the progression of breast cancer." (PMID 33073494, 2020). "Expression of TBC1D9 and CEACAM6 was higher in GATA3 mutant MCF-7 cells, GATA3 mutant CAMA1 cells, and primary GATA3 mutant breast cancer cells, whereas expression of PPT1, CYBRD1, HOXC13, and AFF3 was higher in GATA3 wild type cells." (PMID 29262572, 2017). "The expression of MYBL2, HOXC13, and E2F8 was verified by qRT-PCR assay in breast cancers." (PMID 36814821, 2023).
cervical cancer (6 papers, 2019 to 2023). A primary or metastatic malignant neoplasm involving the cervix. "The aim of this first study in the Mexican population was to search for and analyze variants in the coding region of the HOXC13 and HOXD13 genes in women with cervical cancer." (PMID 36833285, 2023). "In cervical cancer, HOXC13 promotes cell proliferation, migration, invasion and glycolysis by regulating β-catenin/c-Myc pathway." (PMID 38057852, 2023). "In cervical cancer, silencing FZD6 function caused delayed cellular proliferation, invasion, and EMT transition through HOXC13/WNT5A/FZD6 axis." (PMID 35237656, 2022). "HOXC13 facilitates cervical cancer cell proliferation, migration, invasion and glycolysis through the β-catenin/c-Myc signaling pathway." (PMID 35060926, 2022). "Quantitative real-time polymerase chain reaction (qRT-PCR) and Western blot assays have demonstrated that HOXC13 is highly expressed in cervical cancer, metastatic melanoma, liposarcoma, glioblastoma, sarcomas, and esophageal, skin, prostate, and breast cancers." (PMID 36833285, 2023). "In cervical cancer cell model, BMI-1, a gene which encodes a ring finger protein that is the major component of the polycomb group complex 1 (PRC1), is able to modulate HOXC13 expression." (PMID 31137568, 2019). "The involvement of HOXC13 in cell cycle progression, cell growth and carcinogenesis has been well documented: knocking down HOXC13 in human cancer cell lines, such as colorectal, breast, prostate and cervical cancer, significantly affects the viability of cancer cells." (PMID 31137568, 2019). "To date, the analysis of the HOXC13 and HOXD13 genes in cervical cancer is limited to expression studies; thus, the results generated in this initial research work have contributed new information in the hope of enriching the molecular basis of the disease." (PMID 36833285, 2023).
melanoma (6 papers, 2012 to 2025). A malignant, usually aggressive tumor composed of atypical, neoplastic melanocytes. "Forty-eight primary melanoma and corresponding metastatic tissue samples were evaluated for HOXC13 expression by IHC and qRT-PCR." (PMID 39858044, 2025). "In vitro HOXC13 expression confirmed this pattern, in which primary melanoma cell lines had moderate HOXC13 expression, while metastatic cell lines had significantly higher expression." (PMID 39858044, 2025). "In real-world studies, in the glioblastoma and melanoma cohort, the group with higher levels of HOXC13 displayed a worse prognosis after immunotherapy." (PMID 40861477, 2025). "The overexpression of HOXC13 was observed in metastatic melanoma tissues when compared to primary melanoma tissues, implying its role as a metastatic inducer." (PMID 34617205, 2022). "HOXC13 is overexpressed in metastatic melanoma tissues compared to primary melanoma tissues and is targeted by miR‐503 in esophageal squamous cell carcinoma." (PMID 30884206, 2019). "Metastatic tissues had significantly increased HOXC13 expression compared to primary melanoma." (PMID 39858044, 2025). "Moreover we have evaluated HOXC13 expression in melanoma cell lines." (PMID 22583695, 2012). "In addition HOXC13 profile pattern of expression has been evaluated in melanoma cell lines." (PMID 22583695, 2012). "Furthermore, the involvement of particular HOX genes such as HOXC13, HOXD3, HOXA1 in metastasis and invasiveness was recently demonstrated for melanoma, breast and prostate cancer, respectively." (PMID 27363011, 2016).
alopecia (5 papers, 2009 to 2022). Hair loss usually from the scalp. "Loss of Hoxc13 expression in mice causes a fragile hair with an alopecia phenotype, and loss another HOX gene member, Hoxb13, promotes differentiation and enhances wound healing in adult skin." (PMID 27253709, 2016). "The targeted disruptions of the Hoxc4,Hoxc13 and Trps1 genes were reported to cause defects in the thoracic vertebrae, alopecia, and abnormalities in the vibrissae, skull and thoracic vertebrae, respectively." (PMID 19772620, 2009). "Thus, while Foxn1 and Hoxc13 mutations target hair cortex and cuticle alike, the Hq mutant allele causes alopecia by affecting specifically the hair cortex." (PMID 33367954, 2021).
colon cancer (4 papers, 2018 to 2021). "The prognostic signature based on REG1B, TGM6, NTF4, PNMA5, and HOXC13 could divide colon cancer patients into high–risk and low–risk groups, with an AUC of the ROC of 0.771." (PMID 30884206, 2019). "The expression of cyclins regulated by HOXC13 and knockdown of this gene resulted to cell cycle arrest and apoptosis, in the colon cancer cell lines." (PMID 33073494, 2020). "Further studies are still needed to explore the biological functions and underlying molecular mechanisms of REG1B, TGM6, NTF4, PNMA5, and HOXC13 in colon cancer." (PMID 30884206, 2019). "Using these data, we constructed a prognostic signature based on the expression of REG1B, TGM6, NTF4, PNMA5, and HOXC13 which could provide great significant prognostic value for colon cancer." (PMID 30884206, 2019). "We then constructed a prognostic signature based on the expression of REG1B, TGM6, NTF4, PNMA5, and HOXC13 which could provide significant prognostic value for colon cancer." (PMID 30884206, 2019). "In conclusion, our data highlighted an involvement of HOXB13, HOXC13 and HOTAIR in proximal colon cancers pathogenesis and in lymph nodes metastasis progression, highlighting the main role of these markers in prognosis of colon cancer patients." (PMID 30541551, 2018). "Specifically, the aberrant expression of the HOXB13, HOXC13 and HOTAIR in proximal colon cancers could add an important dowel in understanding molecular mechanisms related to tumor pathogenesis in this location." (PMID 30541551, 2018). "We have recently shown their de-regulation in colon cancer, describing the absence of expression of HOXA13, HOXB13, HOXC13 and HOXD13 in the normal colon mucosa, a slight increase in expression in the transitional mucosa, up to in many cases over-expressed in the tumor." (PMID 34208964, 2021).
pure hair and nail ectodermal dysplasia (4 papers, 2017 to 2024). Pure hair and nail ectodermal dysplasia is characterized by the association of onychodystrophy and severe hypotrichosis, which is mainly limited to the scalp but may also affect the eyelashes and eyebrows. "In humans, mutations in Hoxc13 are associated with complete hair loss in pure hair and nail ectodermal dysplasia (PHNED)." (PMID 38338874, 2024).
lung adenocarcinoma (3 papers, 2020 to 2023). A carcinoma that arises from the lung and is characterized by the presence of malignant glandular epithelial cells. "HOXC13, a highly conserved transcription factor involved in morphogenesis of all multicellular organisms, is aberrantly expressed and associated with cancer progression in esophageal cancer, lung adenocarcinoma, and liposarcomas." (PMID 32850410, 2020). "HOXC13 promotes proliferation of lung adenocarcinoma via modulation of CCND1 and CCNE1." (PMID 31992202, 2020).
metastatic melanoma (3 papers, 2012 to 2020). A melanoma that has spread from its primary site to another anatomic site. "HOXC13 has been reported to be upregulated in metastatic melanoma compared to primary tumor tissue." (PMID 27966447, 2017).
Nail dysplasia (3 papers, 2017 to 2024). The presence of developmental dysplasia of the nail. "In human, HOXC13 mutations could cause ectodermal dysplasia with complete hair loss and nail dysplasia, which suggested that HOXC13 played a critical role in keratin regulation and hair follicle development again." (PMID 30139327, 2018). "We have reported a novel mutation in the HOXC13 gene, results in pure hair and nail dysplasia." (PMID 28403827, 2017). "Meanwhile, seven SNPs in Hoxc13 have been identified so far in human studies to cause PHNED in patients with clinical manifestations of complete hair loss and nail dysplasia." (PMID 38338874, 2024).
prostate carcinoma (3 papers, 2016 to 2023). A carcinoma that arises from epithelial cells of the prostate gland. "HOXC13, a homeobox-family transcription factor known to control cell proliferation and differentiation, was found to be upregulated in our recurrent prostate cancer samples." (PMID 27966447, 2017). "Furthermore, knockdown of HOXC13 has been reported to decrease viability of several cancer cell lines in vitro, including the prostate cancer line PC-3ML." (PMID 27966447, 2017). "We show that systemic dysregulation of CRGs is also found in prostate cancer, including a 4-gene signature (HBEGF, HOXC13, IGFBP2, and SATB1) capable of differentiating recurrent from non-recurrent prostate cancer." (PMID 27966447, 2017). "Here we show that a four-gene signature based on HBEGF, HOXC13, IGFBP2, and SATB1 was able to identify patients whose prostate cancer recurred." (PMID 27966447, 2017).
acute myeloid leukemia (2 papers, 2019). Acute myeloid leukemia (AML) is a group of neoplasms arising from precursor cells committed to the myeloid cell-line differentiation. "The chimera protein NUP98/HOXC13 has a pathogenic importance in acute myeloid leukemia (AML), which leads to the deletion of the mutual fusion of the gene." (PMID 31137568, 2019). "Furthermore, NUP98/HOXC13 is of pathogenetic importance in acute myeloid leukemia." (PMID 30884206, 2019).
ameloblastoma (2 papers, 2019 to 2020). The most common odontogenic tumor, arising from the epithelial component of the embryonic tooth and usually affecting the molar-ramus region of the mandible or maxilla. "A large study enrolling different odontogenic tumors, such as ameloblastomas, calcifying cystic odontogenic tumors, ameloblastic fibromas, keratocystic odontogenic tumors and epithelial odontogenic tumors displayed an over-expression of HOXC13 in all lesions except in fibromas." (PMID 31137568, 2019). "HOXC13 is highly expressed in ameloblastoma tissues compared to keratocystic odontogenic tumors and normal mucosa." (PMID 31137568, 2019).
clubfoot (2 papers, 2018 to 2025). The most common congenital deformation of the foot, occurring in 1 of 1,000 live births. "They identified a HOXC13 deletion that segregated with clubfoot in a three-generation family." (PMID 30134936, 2018). "Recent findings have also highlighted HOXC microdeletions overlapping a noncoding region upstream of HOXC13, alongside a point mutation in HOXC11 segregating within a family affected by isolated clubfoot, and another point mutation in HOXC12 that is prevalent among clubfoot patients." (PMID 40746736, 2025).
ectodermal dysplasia (2 papers, 2018 to 2023). "Interestingly, two missense mutations in the homeodomain of HOXC13 caused ectodermal dysplasia." (PMID 30139327, 2018).
glioblastoma (2 papers, 2023 to 2025). The most malignant astrocytic tumor (WHO grade IV). "In glioblastoma, HOXC13 is an important diagnostic and prognostic biomarker." (PMID 38057852, 2023).
leukemia (2 papers, 2010 to 2016). A malignant (clonal) hematologic disorder, involving hematopoietic stem cells and characterized by the presence of primitive or atypical myeloid or lymphoid cells in the bone marrow and the blood. "HOXC13 has additional links to leukemia, because fusions of NUP98 and HOXC13 cause human myeloid leukemia." (PMID 27506447, 2016). "Also, an antagonistic role for SPI1 and HOXC13 in erythroid cell differentiation has been proposed based on data from erythro leukemia cell lines." (PMID 27506447, 2016).
Obesity (2 papers, 2020 to 2024). Accumulation of substantial excess body fat. "Genome-wide association studies (GWAS) identified several variants of developmental regulatory genes that correlate with obesity, including in TBX15 and HOXC13." (PMID 39401200, 2024). "Based on the obtained results, the ZSCAN32, PLCD4, HOXC13, and ADCY9 from obesity predicted genes, as well as LIMA1, and SLC22A23 from CRC predicted genes were significantly related to CRC survival rate." (PMID 33073494, 2020).
breast adenocarcinoma (1 paper, 2023). "On one hand, the analysis indicated that both HOXC13 and HOXD13 can be held as mutational cancer drivers in breast adenocarcinomas and esophageal tumors, respectively, highlighting their proliferation-inducing capacity." (PMID 36833285, 2023).
cervical adenocarcinoma (1 paper, 2016). An adenocarcinoma arising from the cervical epithelium. "Additionally, in human cervical adenocarcinoma cells BMI‐1 knockdown promotes the up‐regulation of HOXC13 expression, contributing to a block in cell proliferation." (PMID 27506447, 2016).
Fibroadenoma (1 paper, 2016). A benign tumor of the breast characterized by the presence of stromal and epithelial elements. "In a separate study by Kuijper interrogating the transcriptome differences between five fibroadenomas and eight phyllodes tumors, CTAG1/2, PRAME, HOXC13, ELF5 and FABP7 were among 96 other transcripts found to be highly differentially expressed between fibroadenomas and phyllodes tumors." (PMID 26961242, 2016).
floor of mouth cancer (1 paper, 2020). "3-mRNA (TGFBR3、KLHL40 and HOXC13) model was identified in the network and that was associated with the clinical outcome of floor of mouth cancer according to univariate and multivariate Cox proportional regression analyses." (PMID 32931492, 2020).
gastric adenocarcinoma (1 paper, 2023). "A previous bioinformatics analysis revealed that HOXC genes (HOXC8, HOXC9, HOXC10, HOXC11, HOXC12, and HOXC13) might participate in pathogenesis of gastric adenocarcinoma." (PMID 37724126, 2023).
hypotrichosis (1 paper, 2024). A congenital condition, usually due to genetic aberrations, that is characterized by a lack of hair growth on the head and/or body. "Ectodermal dysplasia-9 (ED-9) is a congenital disorder with clinical manifestations of hypotrichosis and nail dystrophy, and Hoxc13 is the pathogenic gene for ED-9." (PMID 38338874, 2024).
invasive breast carcinoma (1 paper, 2023). A carcinoma that infiltrates the breast parenchyma. "Furthermore, the Kaplan–Meier dataset plotter was performed to reveal that high expression of MYBL2, HOXC13, and E2F8 had a poor RFS rate in invasive breast cancers." (PMID 36814821, 2023).
leukoplakia (1 paper, 2020). A white patch or plaque on a mucous membrane that cannot be characterized clinically or pathologically as any other disease. "HOXC13 has been reported to be correlated with progression from leukoplakia to OFSCC arising in the Gingivo Buccal Complex (GBC) with integrative genome-wide analysis." (PMID 32931492, 2020).
lipoma (1 paper, 2013). A benign, usually painless, well-circumscribed lipomatous tumor composed of adipose tissue. "In the present study, we evaluated HOXC13 expression in a whole spectrum of adipocytic tumors, including lipomas, WDLPSs, DDLPSs, pleomorphic (PLPS) and MLPSs, associating this analysis to the evaluation of amplification/translocation status of chromosomal region 12q13-15." (PMID 24085196, 2013). "Based on these data, in the current study, we analyzed a series of adipocytic tumors, including well-differentiated LPSs (WDLPSs), dedifferentiated LPSs (DDLPS), myxoid LPSs (MLPSs), pleomorphic LPSs (PLPSs) and lipomas, in order to evaluate HOXC13 expression and 12q13-15 chromosomal locus status." (PMID 24085196, 2013). "In 4 lipoma samples, in 2 MLPSs and in 1 PLPS, HOXC13 gene expression was absent, while it was very low in the other PLPS." (PMID 24085196, 2013).
lung carcinoma (1 paper, 2019). "Knockdown of HOXC13 in lung cancer cell models inhibits cell proliferation blocking G1 phase of cell-cycle." (PMID 31137568, 2019). "HOXC13 is further down-regulated by miR141 in lung cancer cell lines." (PMID 31137568, 2019).